PAX2 (paired box 2)
Diseases named in the same sentence as PAX2 in open-access papers (continued):
Sharing a sentence is not in itself a finding about the gene and the disease.
tumor (continued). "The paired box 2 (PAX2) was among the hub genes of the red-WT module and believed to be a tumor-inducing gene in WT with key role in kidney cell differentiation." (PMID 31988326, 2020). "The immunohistochemical profile of the current tumor is comparable to previously reported TLFCK cases (AE1/AE3+, CK7+, PAX-2+, PAX-8+, vimentin+, EMA+, TTF-1−, TG−, CD56−, WT-1−, CD10−, and CEA−)." (PMID 25133003, 2014). "Thus, it is possible that PAX2 could be an oncogene or tumor suppressor." (PMID 23502471, 2013). "PAX2 and PAX8 are valuable markers in the differential diagnosis of neoplasms, particularly in poorly differentiated tumors or metastatic lesions of unknown primary origin." (PMID 40506992, 2025). "Tumor clusters c5-c8 expressed higher levels of blastemal markers, such as EYA1 and PAX2." (PMID 40098972, 2025). "Pten was selected because (a) single tumor suppressors usually do not yield overt ECs, (b) PTEN is the most frequently mutated gene in EC, and (c) PAX2 silencing and PTEN mutations frequently co-occur in EIN and EC." (PMID 40829174, 2025). "PAX2 expression showed a positive correlation with clinical stage and lymph node metastasis and a negative correlation with tumor differentiation level and HCC-related serum marker levels." (PMID 35028121, 2022). "We also stained PAX2, E‐cadherin and Ki‐67 in our RCC organoids and parental tumours." (PMID 35802820, 2022). "In this study, PAX2 was negative in >95% tumor cells in three cases while GATA3 was negative in >90% tumor cells in all five cases." (PMID 34441384, 2021). "In addition, our study supports a role for PAX2 re-expression in HGSOC as a mechanism to reduce chemoresistant cancer stem-like cells function and tumor relapse." (PMID 33828085, 2021). "However, most of the tumor cells with GATA3 and PAX2 expression demonstrated nuclear immunoreactivity for ER and PR with moderate-to-strong staining intensity." (PMID 34441384, 2021). "In some microscopic foci, individual tumor cells exhibiting strong nuclear PAX2 immunoreactivity were intermingled with those without nuclear PAX2 expression." (PMID 34441384, 2021). "The tumor cells demonstrated loss of E-cadherin, with negative CDX-2, p63, NKX3.1, PAX-2, and PSA expression." (PMID 31638990, 2019). "Among them were known cancer/testis antigen genes (PNMA5, SPATA22, ROR1, and CT45A6) and some new candidates (PAX2, HES4, PEG10, NTN4, PDE10A, and POSTN), these genes could be useful tumor markers and potential therapeutic targets." (PMID 30922328, 2019). "Molecules that increase expression of PAX2 may also increase expression of PAX8, which could then increase the aggressive properties of a tumor cell." (PMID 30096791, 2018). "Taken together our results indicate that methylation does not explain PAX2 different expression levels both when comparing groups of tumours and stages of kidney development." (PMID 23890189, 2013). "Taken together, it is plausible that deregulated expression of PAX2 and EN2 may ultimately promote tumor progression specifically via cancer cell proliferation and survival." (PMID 21566742, 2008). "PAX8 is also highly expressed in endometrium but does not undergo loss in EC, making PAX2 silencing a distinctive signature lesion of the endometrium and, as far as is known, unique among the PAX family as a tumor suppressor in the female reproductive tract or elsewhere." (PMID 40829174, 2025). "Immunohistochemistry corresponds to typical sex cord-stromal tumour profile (positivity for SF1, calretinin, inhibin, vimentin, often FOXL2; often oestrogen and progesterone receptor expression; and negativity or weak patchy staining for keratin, negativity for EMA, PAX8, and PAX2)." (PMID 36399188, 2023).
tumor (continued). "The paired nuclear gene 2 protein (PAX2) and the estrogen and progesterone receptors (ER, PR) are generally negative, indicating that the tumor may not be connected to the patient's hormone level." (PMID 36937446, 2023). "In the same seromucinous tumor category, there was no uniform pattern in PAX2 and PAX8 expression." (PMID 35387670, 2022). "WT1 was originally considered a tumor suppressor gene, repressing the transcription of several growth factors and growth factor receptors including insulin-like growth factor II, insulin-like growth factor receptor, PDGF, TGF β1, PAX2, retinoic acid receptor α and EGR1." (PMID 36818371, 2022). "As shown by our results, PAX2 showed strong predictive efficacy for HCC, with its expression positively correlated with clinical stage, lymph node metastasis, and HCC-related serum markers (CA199, FucAFP, ALD-A, and AFu), and negatively correlated with tumor differentiation level." (PMID 35028121, 2022). "The tumor cells were positive for PAX2 but negative for GATA3." (PMID 33919505, 2021). "First, we categorized clustered data into tumor and stromal populations using a panel of markers for each (epithelial: AQP1, AQP2, EPCAM; endothelial: PLVAP, CD31, CD34; fibroblast: PDGFRα, PDGFRβ; immune: CD45; tumor cell: CXCR4, VIM, KRT18, PAX8, PAX2, CA9, CD10)." (PMID 34884982, 2021). "In three cases, PAX2 expression was absent in >95% (2/5) or 100% (1/5) tumor cells." (PMID 34441384, 2021). "Thus, studying the shared regulatory mechanisms of PAX2 and PAX8 expression between the fallopian tube and ovary will be essential to developing effective treatment therapies until the site of origin of a patient’s tumor can be definitively identified." (PMID 30096791, 2018). "In one tumor (case 4) with focal PAX2 expression, similar to GATA3, there was no significant morphological difference between PAX2-positive and PAX2-negative areas." (PMID 35204416, 2022). "In some microscopic foci, the tumor cells were positive for ER and PR but negative for GATA3 and PAX2, and vice versa." (PMID 34441384, 2021). "Immunohistochemically (IHC), the tumor cells are positive for TFE3 and the renal tubular markers (PAX2 and PAX8), and completely negative for SMARCB1, an oncosuppressor protein." (PMID 27733182, 2016).
cancer (61 papers, 2008 to 2025). A tumor composed of atypical neoplastic, often pleomorphic cells that invade other tissues. "Another study states that the overexpression of PAX2 is linked to cancer, while underexpression causes malformed ureters and hypoplastic kidneys." (PMID 36555181, 2022). "Pax2 is also involved in cell proliferation and carcinogenesis in the endometrium, where it is activated by estrogen and tamoxifen, possibly due to cancer-linked hypomethylation of the Pax2 promoter." (PMID 34195082, 2021). "PAX2 is a transcriptional regulator normally expressed during early stages of development and is implicated as an oncogene in several types of cancers, where its expression is aberrantly increased." (PMID 30575780, 2018). "The PAX proteins are promising because PAX8 is ubiquitously expressed in serous tumors and PAX2 loss is an early molecular event shared in the progression from benign to malignant carcinoma." (PMID 30096791, 2018). "In the normal endometrial tissue, versus precancerous lesions and cancer, the level of the PAX-2 protein loss increases progressively at the rate of 36%, 71%, and 77% respectively." (PMID 24308813, 2013). "Recent reports have associated the transcription factors Pax2 and Pax5 with increased capabilities for cell motility and adhesion in human cancer." (PMID 22531031, 2012). "The diffuse positive nucleus of p16 could suggest the possibility of high grade carcinoma, and the nucleus staining of β-catenin as well as the loss of PAX2 suggest the risk of endometrioid neoplasia and poorer outcomes." (PMID 35796805, 2022). "Importantly, there was a decrease in the expression of CDH2 which has been shown to be positively correlated with PAX2 activity, and is important in signalling stem cell differentiation and has been linked to cancer metastasis." (PMID 34722257, 2021). "This increased expression was associated with cancer-linked hypomethylation of the PAX2 promoter." (PMID 32300484, 2020). "PAX2 has been reported to be mechanistically associated cancer cell proliferation." (PMID 28298218, 2017). "Similarly, the loss of PAX2 expression also correlates with the development of endometrial precancer and cancer." (PMID 23502471, 2013). "Transcription factors encoded by the Pax-2 gene not only have a decisive effect on important organ development, such as the genitourinary system and central nervous system, but also have a close relationship with the occurrence of various organ-based malignant tumors." (PMID 40357279, 2025). "In summary, this study establishes a specific PAX2 epigenetic reprogramming event as a highly recurring cancer-initiating mechanism in EC." (PMID 40829174, 2025). "The TFs captured in Fig F in S1 Text also have known associations with cancer (e.g., KLF4 and PAX2)." (PMID 38206988, 2024). "Rare cancer biomarkers such as Pax8, Pax2, napsinA, carbonic anhydrase IX, claudin-4, Cdx-2, and others have been identified and studied thoroughly to help provide a better diagnosis of rare cancer." (PMID 38256274, 2024). "Our results connect PR response elements with PAX2 and 3D chromatin conformation, which is consistent with the preservation of progestin regulation in differentiated cancer cells expressing hormone receptors." (PMID 35018885, 2022). "We found that PAX2 knockdown by shRNA increased CSC markers at the mRNA and protein level suggesting that loss of PAX2 plays a role in cancer stem cell function." (PMID 33828085, 2021). "Several studies have shown that miR-1915-3p modulates multidrug resistance, anti-apoptosis and stem cell differentiation by targeting BCL2 apoptosis regulator (BCL2), prominin 1 (PROM1) and paired box 2 (PAX2) in multiple types of cancers." (PMID 34774019, 2021).
cancer (continued). "In these DEGs, several cancer‐associated genes such as HOXC10, THBS1, CDKN2B, PAX2 and H19 were significantly associated with AML biology." (PMID 31794134, 2020). "As predicted, significant enrichment in estrogen response signaling was observed in genes downregulated by Tam or PAX2, providing support that PAX2 elicits its antiproliferative effects in ER+ cancer cells, via modulation of ER target genes." (PMID 32843722, 2020). "PAX2 served as an oncogenic transcription factor in various other cancers by reprogramming gene regulatory networks." (PMID 31622355, 2019). "The findings reported here are of potential importance in understanding the role of PAX2 expression in cancer progression and metastasis." (PMID 29928489, 2018). "Of these various cancer types, some subtypes frequently express PAX2 at high levels, whereas in the surrounding normal adult tissue the PAX2 expression is repressed following cessation of development." (PMID 29928489, 2018). "Increased methylation of the PAX2 promoter was observed in both cancer tissues and cell lines and was positively correlated with PAX2 expression." (PMID 27764784, 2016). "In recent years, research on PAX2 has gradually expanded to cancer, including kidney cancer, breast cancer, colon cancer, and cancers of the female reproductive tract." (PMID 27764784, 2016). "Apoptosis was induced in cell lines following RNA interference to silence PAX2 expression, suggesting that endogenous PAX2 gene expression is required for the growth and survival of cancer cells." (PMID 19467152, 2009). "This further implicates En-2 as a therapeutic target for cancer either directly or indirectly via targeting PAX2." (PMID 21566742, 2008). "During tumorigenesis, PAX2 may also promote cancer cell proliferation and invasion by enhancing the formation of vascular-like structures." (PMID 40948392, 2025). "With regard to PAX2, it seems to be involved in the promotion of fatty acid metabolic reprogramming, a shift from normal oxidative metabolism to lipid biosynthesis pathways that support rapid cancer cell growth and survival." (PMID 40506992, 2025). "Although developed to explain PAX2 transcriptional silencing, we speculate that our pearl necklace model could be generalized to other cancer drivers." (PMID 40829174, 2025). "Furthermore, novel inhibitors of PAX2 have been shown to suppress cancer cell proliferation in vitro." (PMID 37511191, 2023). "Such inhibitors can suppress the proliferation of PAX2-expressing cancer cells and may provide scaffolds for future anti-cancer compounds." (PMID 37628926, 2023). "Similarly, exosomal miR-744 was able to rescue sorafenib sensitivity in resistant HepG2 cancer cells, by targeting PAX2, involved in the regulation of chemotherapy response in several cancers." (PMID 35912267, 2022). "Interestingly, loss of the transcription factor PAX2, which is a common and early alteration in HGSOC, played a pivotal role in the expression of cancer stem-like cells (CSC) markers and cell function." (PMID 33828085, 2021). "However, the mechanisms by which PAX2 expression is regulated in cancer remain relatively poorly understood, and in particular the mechanisms associated with repression of PAX2 expression." (PMID 29928489, 2018). "We observed that the promoter sequences of these translation elongation factor genes harbour binding sites for transcription factors which are commonly deregulated in the pathogenesis of human cancers, such as cFos, cJun, c-Ets1, Sp1, Sp3, Pax2 and, Pax6 among others." (PMID 29342219, 2018). "Interestingly, HER2, PAX2, AHR, AR, and RUNX factors have each been implicated in cancer stem cell biology (and see “Discussion”)." (PMID 28412963, 2017). "PAX2 can function as a cancer promoter or suppressor depending on the genetic background." (PMID 27764784, 2016).
cancer (continued). "Interestingly, the stroma in the cancers exhibited reduced PAX2 expression compared with hyperplasia and proliferative endometrium; however, atrophic endometrium also exhibited reduced stromal PAX2 expression." (PMID 27764784, 2016). "PAX2 expression has been shown to be involved in cancer cell survival." (PMID 21876729, 2011). "However, in some cancers PAX2 and other PAX proteins are aberrantly overexpressed." (PMID 34722257, 2021). "Both PAX2 and PAX8 can modulate similar cellular pathways, such as proliferation, differentiation, survival, metastasis and metabolism in a cancer context." (PMID 40506992, 2025). "PAX2 regulates the expression of key enzymes in fatty acid synthesis, such as FASN (Fatty Acid Synthase), which is commonly overexpressed in cancers." (PMID 40506992, 2025). "Upregulation of ETS TFs (primarily ERG) and downregulation of PAX2 are observed in approximately 20% of PIN and approximately 80% of EIN lesions, respectively, and facilitate transition to carcinoma." (PMID 40829174, 2025). "Pax2 binds to the promoter of a disintegrin and metalloproteinase domain-containing protein 10 (ADAM10), a metalloprotease that plays a crucial role in cancer progression and metastasis." (PMID 34195082, 2021). "The 13 overexpressed genes were reported to play a role in RCC: PAX2, NAT8, GBA3, SLC22A2 other cancer types: AOC1, HAO2, TMEM27, cell death (NPR3) or kidney metabolism: TMEM171, CYS1." (PMID 31150395, 2019). "PAX2 expression is stronger in LMP tumors and lower in more aggressive cancer types like HGSC." (PMID 40506992, 2025). "Paired box gene 2 (PAX2) is one of 9 mammalian paired box DNA-binding transcription factors (TFs) (PAX1–9) with diverse roles in cell proliferation, lineage determination, organogenesis, and cancer." (PMID 40829174, 2025). "We hypothesize that this compound will have similar effects in other cancer cell types which also aberrantly express PAX proteins at a high level, particularly PAX2, and potentially PAX5, PAX6 or PAX8." (PMID 34722257, 2021). "Altogether, these findings support the hypothesis that high PAX2 expression inhibits cell growth and PAX2 expression improves the efficacy of Tam in ER+/HER2− cancer cells." (PMID 32843722, 2020). "PAX2 is lost early in the molecular progression of fallopian tube derived cancer and is absent in ~85% of HGSC." (PMID 30096791, 2018). "EG1 binds the pared domain of Pax2, resulting in an inhibition of Pax2/DNA binding and subsequent target genes expression control, as well as reduced cell survival in renal cell (RCC11) and ovarian (SKOV-3) carcinoma models." (PMID 29921764, 2018). "The aim of this study was to define the role of PAX2 in OVE cells, characterizing specifically its potential involvement in the regulation of stem cell-like behaviors that may be relevant to cancer-initiating cells." (PMID 29100356, 2017). "Meanwhile, uniform PAX2 immunoreactivity is rarely observed in atypical hyperplasia/endometrioid intraepithelial neoplasia or carcinoma; lack of PAX2 in endometrial hyperplasia suggests cytological atypia or architectural complexity." (PMID 27322430, 2016). "Further differentiating them from renal epithelial tumors, melanotic Xp11 cancers are unique in their lack of reactivity with PAX-2 and PAX-8." (PMID 24735727, 2014). "Atypical endometrial hyperplasia/EIN and EC shares several molecular alterations with each other, including microsatellite instability, PAX2 inactivation, mutation of PTEN, KRAS, and CTNNB1 (β-catenin), but there is not a linear accumulation of mutational events leading to cancer." (PMID 31293968, 2019). "In contrast, TGF-β–mediated suppression of PAX2 expression might not be universal to all cancer types." (PMID 29928489, 2018).
cancer (continued). "The aim of this study was to define the role of PAX2 in oviductal epithelial (OVE) cells and its response to transforming growth factor β1 (TGFβ), characterizing specifically its potential involvement in regulating stem cell-like behaviors that may contribute to formation of cancer-initiating cells." (PMID 29100356, 2017). "Among the genes downregulated after MLL1 and MLL2 downregulation in our RNA-seq data, we detected three additional transcription factors with known roles in cancer: MYC, PAX2, and BAHCC1 (data not shown)." (PMID 34381018, 2021).